HMGB1 (high mobility group box 1)
Diseases named in the same sentence as HMGB1 in open-access papers (continued):
Sharing a sentence is not in itself a finding about the gene and the disease.
tendinopathy (12 papers, 2016 to 2024). "Although extensive literature is available on the inflammatory role of HMGB1 in fibrosis and other diseases, only limited studies have linked HMGB1 to tendinopathy." (PMID 31560698, 2019). "The concomitant increase in the expression of TREM-1, RAGE and HMGB1 with respect to inflammation associated with glenohumeral arthritis and sterile inflammation signifies the involvement of these molecules in tendinopathy." (PMID 27792788, 2016). "By using in vivo and in vitro models, we show for the first time that HMGB1 induces inflammatory reactions in tendon cells and tendon matrix, a hallmark of early stages of tendinopathy, and injection of HMGB1 inhibitor, GL, abolishes the development of tendinopathy." (PMID 31560698, 2019). "Alarmins including HMGB1 are implicated as key effectors in the activation of immune system that may be important in the pathogenesis of tendinopathy." (PMID 31560698, 2019). "Moreover, a few more recent studies have shown that upregulation of HMGB1 is associated with shoulder tendon injury/tendinopathy in patients and indicated that it would be a valuable target for tendinopathy management." (PMID 31560698, 2019). "Our study provides evidence that HMGB1 could operate as a damage-associated modulator of early tendinopathy." (PMID 28879051, 2017). "In recent years, accumulating evidence has shown that HMGB1 plays crucial roles in the pathogenesis of tendinopathy." (PMID 38633380, 2024). "Our previous research has also indicated that in chronic Achilles tendon disorders, such as tendinopathies, HMGB1 release induced by stress or injury can initiate inflammatory pathways that lead to tissue degradation." (PMID 38139865, 2023). "Notwithstanding with OA studies, the presence of HMGB1 decreases inflammation in tendinopathy and is necessary for tendon healing, an effect attributed to the chemotactic actions of HMGB1 in stem cells." (PMID 35159924, 2022). "HMGB1 is shown to be present in human tendinopathy, and it can regulate inflammatory cytokines and matrix changes." (PMID 33603790, 2021). "In conclusion, this study shows that HMGB1 released to tendon matrix due to mechanical overloading induces tendinopathy development by initiation of tendon inflammation and eventual tendon degeneration." (PMID 31560698, 2019). "Additional clinical studies support this finding showing enhanced levels of HMGB1 in early stage supraspinatus tendinopathy tissues and late stage tendinopathy tissues as well." (PMID 31560698, 2019). "Collectively, these findings point to HMGB1 as a key molecule that is responsible for the induction of tendinopathy due to mechanical overloading placed on the tendon." (PMID 31560698, 2019). "Based on the findings in this study, we propose a pathological tendinopathy model focusing on the role of HMGB1 in tendinopathy development and the subsequent degenerative changes." (PMID 31560698, 2019). "The findings of this study provide evidence for the role of HMGB1 as a therapeutic target to prevent tendinopathy before its onset and block further development at its early inflammation stages." (PMID 31560698, 2019). "The findings of this study further links HMGB1 with the inflammatory responses induced by mechanical overloading of tendon to the developmental course of tendinopathy." (PMID 31560698, 2019). "In this study, we extend these investigations to examine the role of HMGB1, an inflammatory alarmin molecule, in tendinopathy development due to mechanical overloading placed on the tendon." (PMID 31560698, 2019). "Recent findings with clinical samples of tendinopathy indicate that HMGB1 is present and likely plays an important role in driving early stages of tendinopathy." (PMID 31560698, 2019). "This suggests that HMGB1 plays a similar role in the development of mechanical overloading-induced tendinopathy in humans." (PMID 31560698, 2019).
tendinopathy (continued). "Taken together, the enhanced production of these mediators in the presence of HMGB1 supports a role for this protein in the amplification of the inflammatory response of human tendon disease." (PMID 28879051, 2017). "Herein we demonstrate that HMGB1 is present in early tendinopathy biopsies and thereafter in mechanistic studies demonstrate that HMGB1 likely contributes to regulation of inflammatory and matrix pathways in tendon cells via TLR4 signalling." (PMID 28879051, 2017). "Tendinopathic tissues demonstrated significantly increased levels of the danger molecule HMGB1 compared with control tissues with early tendinopathy tissue showing the greatest expression." (PMID 28879051, 2017). "HMGB1 message and protein were significantly upregulated in early tendinopathy samples compared with control and torn tendon samples." (PMID 28879051, 2017). "Furthermore, our prior investigations into tendinopathy have revealed that HMGB1 release triggered by stress or injury can activate inflammatory pathways leading to tissue inflammation and degradation." (PMID 39331598, 2024). "High mobility group box 1 (HMGB1), a ubiquitous protein present in all cells and a potent inflammatory mediator, has been implicated in the pathogenesis of various inflammatory diseases, including tendon overuse injuries such as tendinopathy." (PMID 38139865, 2023). "However, there has been limited data regarding the potential role of HMGB1 in tendinopathy development." (PMID 31560698, 2019). "Since dysregulated matrix remodelling is a feature of tendinopathy, we next considered whether HMGB1 might alter differential matrix synthesis in vitro." (PMID 28879051, 2017). "HMGB1 is present in human tendinopathy and can regulate inflammatory cytokines and matrix changes." (PMID 28879051, 2017). "Specifically, S100A9 and HIF-1α may have pro-inflammatory effects in tendon disease, nuclear IL-33 may be protective against pro-inflammatory stimuli and HMGB1 may have a potential role in tendon healing." (PMID 28761710, 2017). "Therefore, we suggested that HMGB1 could be a potential alarmin for tenocyte senescence in tendinopathy." (PMID 38309291, 2024). "However, whether HMGB1 mediates the development of tendinopathy due to mechanical overloading placed on the tendon is largely unknown." (PMID 31560698, 2019). "While it is currently unclear whether our findings will reflect the actual mechanisms of tendinopathy development and treatment in humans, recent studies demonstrated that HMGB1 is present in human tendinopathic tendons and regulates cellular inflammation and protein production in vitro." (PMID 31560698, 2019). "Moreover, there are little data regarding the potential roles of S100A9 and HMGB1 in tendinopathy." (PMID 28761710, 2017). "This is supported by the finding that use of GL, a specific inhibitor of HMGB1, suppresses inflammatory responses as defined by PGE2 in tendon cells and prevents tendinopathy development." (PMID 31560698, 2019). "Thus, HMGB1 may represent a new target of therapy for tendinopathy." (PMID 31560698, 2019). "Although previous studies have indicated the vital role of HMGB1 in tendinopathy and in the regulation of stem cells, no studies have focused on the role of HMGB1 in TSPCs during diabetic tendinopathy." (PMID 38633380, 2024). "We propose HMGB1 as a mediator driving the inflammatory/matrix crosstalk and manipulation of the HMGB1/TLR4 axis may offer novel therapeutic approaches targeting inflammatory mechanisms in the management of human tendon disorders." (PMID 28879051, 2017).
triple-negative breast carcinoma (12 papers, 2019 to 2025). An invasive breast carcinoma which is negative for expression of estrogen receptor (ER), progesterone receptor (PR), and human epidermal growth factor receptor 2 (HER2). "This study investigates metformin’s effects on the HMGB1/RAGE signaling pathway in triple-negative breast cancer (TNBC) cells." (PMID 40277915, 2025). "Human and mouse triple-negative breast cancer cells, MDA-MB-231 and 4T1, along with HMGB1-deficient mouse embryonic fibroblast cells, were cultured." (PMID 40389855, 2025). "Key studies using multiple mouse tumors, including a triple-negative breast cancer, showed that HMGB1 drives the differentiation of MDSCs from bone marrow progenitor cells, demonstrating that HMGB1 acts at the earliest stages of MDSC development." (PMID 36831371, 2023). "Specifically, HMGB1 prompts the release of neutrophils’ extracellular traps, favoring the development of lung metastasis in triple-negative breast cancer mouse models." (PMID 38203626, 2023). "For example, HMGB1 promotes lung metastasis in triple-negative breast cancer by inducing CD62Ldim neutrophil polarization." (PMID 36204682, 2022).
alcoholic liver diseases (11 papers, 2014 to 2025). A disorder caused by damage to the liver parenchyma due to alcohol consumption. "Various isoforms of HMGB1, such as disulphide-linked hyperacetylated HMGB1, were observed in the serum of both ethanol-treated mice and patients with alcoholic liver disease." (PMID 37298365, 2023). "Boosted HMGB1 protein production in hepatocytes was demonstrated to exacerbate alcoholic liver disease." (PMID 38290384, 2024). "Hepatocytes have been shown to be the source of these isoforms; thus, HMGB1 derived from hepatocytes is thought to be involved in the pathogenesis of alcoholic liver disease." (PMID 37298365, 2023). "In liver I/R and non‐alcoholic liver disease, extracellular HMGB1 was conscientious for the inflammation to hepatic injury." (PMID 32596881, 2020). "This suggests that hepatocyte HMGB1 participates in the pathogenesis of alcoholic liver disease and that HMGB1 undergoes PTMs that are involved in the mechanism of hepatotoxicity." (PMID 27713681, 2016). "Analysis of serum from mice and human subjects with alcoholic liver disease by LC–ESI/MS also revealed an increase in oxidation of HMGB1 to the disulfide isoform." (PMID 27713681, 2016). "In alcoholic liver disease, HMGB1 translocates from the nucleus to the cytoplasm in hepatocytes, increasing apoptosis signal-regulating kinase 1-positive hepatocytes, passive HMGB1 release, and NLRP3 inflammasome activation, promoting inflammation and hepatic fibrosis." (PMID 40688353, 2025). "Additionally, the activation of nucleocytoplasmic translocation and secretion from the hepatocytes induced an elevated expression of HMGB1 in rodent models of alcoholic liver disease." (PMID 33142949, 2020). "Interestingly, in alcoholic liver disease, serine-34 is also phosphorylated in the hyperacetylated HMGB1." (PMID 27713681, 2016). "The HMGB1/TLR4 signalling pathway is being considered as a potential and promising therapeutic target, particularly for patients with alcoholic liver disease." (PMID 37298365, 2023). "Therefore, the BRD4/HMGB1 pathway is involved in alcohol‐induced liver injury, and manipulation of this pathway through strategies such as SAA treatment holds great therapeutic potential for the treatment of alcoholic liver diseases." (PMID 32596881, 2020).
allergic rhinitis (11 papers, 2020 to 2025). Inflammation of the nasal mucous membranes caused by an IgE-mediated response to external allergens. "Recent studies demonstrated that EP attenuated inflammatory response of murine allergic rhinitis by decreasing HMGB1 expression." (PMID 33737667, 2021). "HMGB1 is involved in the induction of nasal diseases in patients with allergic rhinitis (AR), chronic rhinosinusitis (CRS), and eosinophilic chronic rhinosinusitis (ECRS)." (PMID 34445093, 2021). "High mobility group box 1 was released in the nasal mucosa of allergic rhinitis mice." (PMID 33707120, 2022). "High mobility group box 1 protein participates in the pathogenesis of allergic rhinitis." (PMID 33707120, 2022). "These may contribute to the translocation of high mobility group box 1 and the development of allergic rhinitis." (PMID 33707120, 2022). "Recently, studies demonstrated that HMGB1 was highly expressed in epithelial cells and inflammatory cells of patients with chronic rhinosinusitis and allergic rhinitis, and patients with severe symptoms have the highest serum levels and the highest extracellular expression of HMGB15,17." (PMID 33737667, 2021). "The one study that examined the possible role of RAGE in allergic rhinitis found high levels of mRNA expression of HMGB1 in nasal brushings of those with allergic rhinitis compared to those that did not, though levels of RAGE were not different between the two groups." (PMID 32846877, 2020). "This research aimed to explore the serum high-mobility group box 1 (HMGB1) and high-mobility group box 2 (HMGB2) levels in allergic rhinitis (AR) children and its correlation with clinical results." (PMID 37713866, 2023). "High mobility group box-1 (HMGB1) increased by TGF-β1 is involved in the induction of nasal inflammation and injury in patients with allergic rhinitis, chronic rhinosinusitis, and eosinophilic chronic rhinosinusitis." (PMID 34445093, 2021). "It is plausible that HMGB1 promotes neoangiogenesis through the expression of vascular endothelial growth factor (VEGF) as occurs in chronic immune-mediated diseases and allergies such as allergic rhinitis." (PMID 34445745, 2021).
Allergy (11 papers, 2014 to 2025). An allergy is an immune response or reaction to substances that are usually not harmful. "Due to damage, stress and inflammatory mediators that can be caused by toxic substances to cells, HMGB1 will be expressed both intracellularly and extracellularly with end results involved some cytokines in infection condition, metabolic disorder, allergy and traumatic injury." (PMID 35340325, 2022). "It was found that HMGB1, HMGB2, IL-6, IL-1β, and family history of allergy were the risk factors for AR." (PMID 37713866, 2023). "RAGE and HMGB1 expression levels in tissues were correlated with disease severity assessed by nasal endoscopy, CT scan, number of previous sinus surgeries, allergy status and nasosinusal microbiology." (PMID 25503556, 2015). "Finally, we found that HMGB1, HMGB2, IL-6, IL-1β, and family history of allergy were the risk factors for AR." (PMID 37713866, 2023). "Thus, it would be important to future evaluate whether HMGB1 would be a therapeutic target for allergy." (PMID 27826297, 2016). "The results demonstrated that allergens can result in allergic diseases accompanied by alteration of PEBP1, HMGB1 and TLR4 levels via miR-205-5P." (PMID 35635016, 2022). "Inhibition of miR‐138‐5p in hMSCs enhanced its effects in attenuating inflammatory responses and allergic reaction in the ARAS model, which is presumably regulated by SIRT1 and the HMGB1/TLR4 pathway." (PMID 33973707, 2021).
anemia (11 papers, 2018 to 2024). A reduction in the number of red blood cells, the amount of hemoglobin, and/or the volume of packed red blood cells. "Systemic HMGB1 administration also caused anemia with extramedullary erythropoiesis just like CLP surviving mice." (PMID 32265930, 2020). "In particular, high levels of HMGB1 and S100A8/A9 were strongly associated with anemia, which has a multifactorial pathogenesis and remains an unmet medical need in patients with MF." (PMID 39391311, 2024). "As a result, HMGB1 reduces the proliferation and increases cell death of erythroid precursors to exacerbate anemia." (PMID 36434065, 2023). "HMGB1 was also recently identified as a key mediator of the anemia of inflammation by physically displacing the binding of erythropoietin to its cognate receptor." (PMID 36434065, 2023). "The damage-associated high-mobility group box-1 (HMGB1) protein suppresses bone marrow cellularity and mediates an anemia that has been reversed with administration of anti-HMGB1 monoclonal antibodies in mice." (PMID 35514362, 2022). "Furthermore, administration of recombinant HMGB1 to healthy mice mediated the anemia and extramedullary erythropoiesis with a significant elevation in reticulocyte counts." (PMID 30134792, 2018). "Another interesting finding is the deletion of HMGB1 in a lethal rodent parasite strain, Pb ANKA, leading to complete protection from mortality due to anemia and cerebral malaria." (PMID 39341498, 2024). "This study found a significant moderate correlation between anemia with VDR and HMGB1 in HIV infection." (PMID 33664952, 2021). "There were moderate correlation between anemia with VDR and HMGB1 (r = 0,518, r = −0,518; p < 0,001)." (PMID 33664952, 2021). "HMGB1 has also been reported to be the mechanism of various cytopenia diseases, even though not directed on HSCs, such as chronic idiopathic neutropenia (CIP), immune thrombocytopenia (ITP), anemia of inflammation (AI), and BMF." (PMID 37223096, 2023). "However, there was no previous study that reported the association between anemia with VDR and HMGB1 in HIV infection." (PMID 33664952, 2021).
Encephalopathy (11 papers, 2018 to 2025). Encephalopathy is a term that means brain disease, damage, or malfunction. "Negating the inflammatory cascade, by targeting HMGB1, may be a strategy to complement non-pharmacologic interventions directed against encephalopathy." (PMID 37048161, 2023).
endometrial cancer (11 papers, 2016 to 2025). Primary or metastatic malignant neoplasm involving the endometrium (mucous membrane that lines the endometrial cavity). "For example, loss of high-mobility group box-1 is associated with both endometrial cancer and implantation defects." (PMID 37310452, 2023). "Notably, miR-218 binds directly to the 3’-UTR of the HMGB1 gene, the upregulation of which induces resistance to paclitaxel in endometrial cancer cells by promoting autophagy." (PMID 34445745, 2021). "Interestingly, a previous study reported that HMGB1 regulated autophagy during chemotherapy in endometrial carcinoma cells." (PMID 33815277, 2021). "In another study, Herpes simplex type 2 virus (HSV-2) infection reduced HMGB1 expression in HEC-1 cells, derived from human endometrial cancer, which were used as a model of epithelial cells." (PMID 32796569, 2020). "It has been shown that overexpression of micro(mi)RNA-218 sensitized paclitaxel resistant endometrial carcinoma cells to paclitaxel by binding to the 3′-UTR of the HMGB1 gene, with downregulation of HMGB1 expression and suppression of HMGB1-mediated autophagy." (PMID 26925422, 2016). "It should be stressed that HMGB1 is a RAGE ligand, as the RAGE-HMGB1 interaction may have a strong impact on the progression of endometrial carcinoma." (PMID 39335163, 2024).